CXCL12 (C-X-C motif chemokine ligand 12)
Diseases named in the same sentence as CXCL12 in open-access papers (continued):
Sharing a sentence is not in itself a finding about the gene and the disease.
osteoarthritis (30 papers, 2006 to 2025). A noninflammatory degenerative joint disease occurring chiefly in older persons, characterized by degeneration of the articular cartilage, hypertrophy of bone at the margins and changes in the synovial membrane. "In this study, we evaluated the effect of the CXCL12/CXCR4 axis on TIMP-3 expression in rats with post-traumatic osteoarthritis (PTOA) and explored the underlying mechanism(s)." (PMID 32038242, 2019). "In osteoarthritis, CXCL12 induced uncontrolled patient-derived osteoblast proliferation and release of cartilage-degrading enzymes by and necrosis of chondrocytes." (PMID 36725964, 2023). "The team found that mTORC1 activation of subchondral preosteoblasts promoted osteoarthritis by stimulating abnormal subchondral bone formation and secretion of CXCL12, promoting cartilage degeneration." (PMID 30792936, 2019). "RA synovial tissues had higher levels of CXCL12 on the endothelium than osteoarthritis (OA) tissues; in both, CXCL12 colocalized to heparan sulfate proteoglycans (HSPGs) and high endothelial venules." (PMID 16507142, 2006). "We evaluated the role of the CXCL12/CXCR4 (C-X-C motif chemokine ligand 12/C-X-C chemokine receptor type 4) axis in aggrecanase-mediated cartilage degradation, and explored the underlying mechanism in a post-traumatic osteoarthritis rat model." (PMID 27690009, 2016). "The C-X-C motif chemokine 12 (CXCL12) and its receptor CXCR4 are pivotal in tissue regeneration and inflammation, yet their role in osteoarthritis (OA) remains ambiguous." (PMID 41331944, 2025). "Inhibition of the CXCL12/CXCR4 signaling axis slows aggrecanase-mediated catabolic processes and lessens the pathological progress of osteoarthritis." (PMID 27690009, 2016). "We evaluated expression of CXCL12/CXCR4 and TIMP-3 in the knee joints of rats with and without osteoarthritis (OA) by immunohistochemistry, immunofluorescence, Western blotting, and enzyme-linked immunosorbent assay (ELISA)." (PMID 32038242, 2019).
multiple sclerosis (29 papers, 2012 to 2026). A progressive autoimmune disorder affecting the central nervous system resulting in demyelination. "In multiple sclerosis, the loss of CXCL12 occurs from abluminal surfaces in the CNS, while CXCR7 expression increases as a scavenger of CXCR12." (PMID 32098047, 2020). "Demyelination and axonal degeneration, hallmarks of multiple sclerosis (MS), are associated with the central nervous system (CNS) inflammation facilitated by C-X-C motif chemokine 12 (CXCL12) chemokine." (PMID 26747276, 2016). "CXCL12 has been found highly expressed in active multiple sclerosis lesions and appears to play a role in enhancing the inflammatory response in multiple sclerosis." (PMID 38368354, 2024). "In active multiple sclerosis, CXCR4 + leukocytes are trafficked to the brain lesions to cause tissue damage by CXCL12 secreted by endothelial cells." (PMID 38684986, 2024). "Imbalances in the CXCL12/CXCR4/ACKR3 axis are associated with diseases, including cancer, multiple sclerosis, and RA." (PMID 34489952, 2021). "In fact, CXCL12 was shown to be upregulated in the CSF of patients with multiple sclerosis or neurological disease, and this was correlated with an increased migration of B cells and T cells into the CNS." (PMID 31752904, 2019). "For example, in the serum of Cx3cr1−/− mice, the levels of ICAM1 were reduced and those of CXCL12 were elevated, oppositely to the changes observed in these molecules during an inflammatory condition, such as multiple sclerosis." (PMID 29251592, 2017). "Interestingly, in mouse models of multiple sclerosis, T cells that have passed BBB-associated ECs are restricted to the perivascular niche by CXCL12 localised to the basolateral surface of these ECs." (PMID 35464424, 2022). "Furthermore, there is evidence suggesting that CXCL12 plays a role in inflammation in multiple sclerosis (MS)." (PMID 34216357, 2022). "Finally, a cross-disease study was performed to monitor CXCL12 levels in sALS, multiple sclerosis (MS), Alzheimer’s disease (AD), frontotemporal dementia behavioral variant (FTD), and type III spinal muscular atrophy (SMA)." (PMID 33213069, 2020). "They found the combination of chitinase-3-like-1, CXCL10, CXCL12, CXCL13 increased the AUC for predicting conversion to clinically definite multiple sclerosis after first attack above any single biomarker in isolation." (PMID 38368354, 2024). "An altered pattern of CXCL12 expression in brain has been reported in multiple sclerosis, suggesting the involvement of the CXCR4/CXCL12 axis in the leukocyte infiltration that characterizes this pathology." (PMID 27766097, 2016). "The second group of researchers demonstrated that CSF concentrations of CXCL12 were significantly higher in patients with amyotrophic lateral sclerosis and multiple sclerosis, but were not altered in AD, spinal muscular atrophy, or frontotemporal dementia." (PMID 37685973, 2023).
lymph node metastasis (28 papers, 2005 to 2025). "CXCL12 expression in 121 cases of LARC was positively associated with lymph node metastasis and pTNM staging (p = 0.011 and p = 0.005, respectively)." (PMID 34976180, 2022). "The CXCR4 expression was correlated with lymph node metastasis, and the expression intensity of CXCL12 was associated with the volume of ascites." (PMID 24765180, 2014). "The CXCR4/CXCL12 axis is significantly associated with lymph node metastasis and poor prognosis." (PMID 41445742, 2025). "On the other hand, higher CXCL12 expression was significantly associated with more advanced stages, worse prognosis, and more lymph node metastasis (N2 showed higher CXCL12 than N0)." (PMID 36699696, 2022). "Other reports found linkage between high tumoral CXCL12 expression levels and both a higher T score and an increased tendency to form lymph node metastasis." (PMID 30257500, 2018). "We detected positive CXCL12 expression, lymph node metastasis, lymphatic invasion and vessel invasion as predictive markers of RFS." (PMID 27439769, 2016). "The investigators concluded that CXCL12 expression is an important predictor of lymph node metastasis and poor prognosis of ESCC patients' survival." (PMID 27041792, 2016). "Immunohistochemical analysis showed the co-expression of CXCR4 and CXCL12 correlated with lymph node metastasis and TNM stage (p < 0.01)." (PMID 24810923, 2014). "Through immunohistochemistry, CXCL12 protein in the cytoplasm of tumor cells was located as well, and CXCL12 expression was observed to be higher in lymph node metastasis tumors than in primary tumors." (PMID 20181250, 2010). "Indeed, in our study, only cell cultures derived from patients with lymph node metastases produced CXCL12 (N0 = 0 pg/mL compared to N1–3 = 8331.3 ± 2357.1 pg/mL)." (PMID 25949860, 2015). "Additionally, a significant correlation between the expression pattern of the CXCL12/CXCR4 axis with lymph node metastasis was identified (P<0.05), excluding gender, age, tumor node metastasis (TNM) stage and differentiation (all P>0.05)." (PMID 23181100, 2012). "For lymph node metastasis, ten CpGs from six genes were found to be significant: CDH1 (site 10), CDH13 (sites 7 and 8), MINT3 (sites 3 and 4), CXCL12 (sites 1 and 3), RARB (site 6) and APC (sites 1 and 6)." (PMID 25052224, 2014). "For lymph node metastasis, there was no clear association between CCL2, CXCL12 SNPs with lymph node status." (PMID 39703847, 2024). "Therefore we examined CXCL12 and CXCR4 immunoreactivity in a subset of 61 matching lymph node metastases." (PMID 20386750, 2010).
cervical carcinoma (27 papers, 2013 to 2025). A carcinoma arising from either the exocervical squamous epithelium or the endocervical glandular epithelium. "To date, polymorphisms in only one chemokine gene, CXCL12, have been reported in relation to cervical carcinoma." (PMID 28280748, 2017). "Treatment targeting the CXCL12/CXCR4 pathway increased the efficacy of radiotherapy of locally advanced cervical cancer." (PMID 36419891, 2022). "Exogenous treatment with recombinant CXCL12 inhibited metastasis-promoting cell migration, cell invasion, and anchorage-independent cell growth events in cervical cancer cell lines (HeLa, SiHa and C-33A)." (PMID 34833360, 2021). "The transcriptional level of CXCL1/3/5/6/8/9/10/11/13/16 in cervical cancer tissues was significantly elevated, while the transcriptional level of CXCL12/14 was significantly lower than that of adjacent cancer tissue." (PMID 34321012, 2021). "The CXCL12/CXCR4 signaling pathway plays an important role in the development of cervical cancer, the further course of this malignant disease, the development of metastases, and the response to radiation therapy." (PMID 34833360, 2021). "In cervical cancer cell lines and primary tumor biopsies, CXCL12 is often downregulated and its promoter is hypermethylated." (PMID 34833360, 2021). "In vitro experiments were carried out to further evaluate the effect of CXCL12 on the proliferation of cervical cancer cells." (PMID 34833360, 2021). "The dominant member of the CXC chemokine subfamily concerning cervical cancer is CXCL12 resulting in 52 PubMed hits." (PMID 34833360, 2021). "And studies showed that CXCL12/CXCR4 pathways was associated with HPV infection as a co-factor, which means a high risk to the incidence of cervical cancer." (PMID 33344075, 2020). "The CXCL12/CXCR4 chemokine pathway is involved in cervical cancer pathogenesis and radiation treatment (RT) response." (PMID 31239542, 2019). "The results provide a strong rationale for future clinical trials of RTCT and plerixafor or another CXCL12/CXCR4 inhibitor aimed at improving the efficacy of frontline curative therapy for patients with cervical cancer and possibly other malignancies." (PMID 31239542, 2019). "One North American study investigated the role of several CXCL12 SNPs in cervical cancer and identified one intronic SNP (rs266085), where the minor allele was associated with a decreased risk of cervical cancer." (PMID 28280748, 2017). "The CXCL12/CXCR4 chemokine pathway is expressed in cervical cancer." (PMID 34833360, 2021). "We showed that four miRNAs (miR-502, miR-145, miR-142, and miR-33b) are independent and common prognostic biomarkers for patients with cervical cancer, and seven proteins (CXCL12, IGF1, PTPRC CDH5, RAD51B, REV3L, and WDHD1) are key genes significantly related to lymph node metastasis." (PMID 32457603, 2020). "In conclusion, this study demonstrates that RTCT increases CXCL12/CXCR4 signalling in cervical cancer, leading to intratumoral accumulation of MDSCs and other myeloid cell populations that may contribute to disease recurrence." (PMID 31239542, 2019). "A large number of studies have demonstrated that chemokines are involved in the progression, migration, and survival of cancers, such as CXCL12 (ENSG00000107562), CCL21 (ENSG00000137077), and especially CCL19 (ENSG00000172724), which is associated with progression of cervical cancer." (PMID 28970820, 2017). "Therefore, the key gene CXCL12, enriched in cell adhesion, may lead to cervical cancer lymph node metastasis by affecting cell-cell adhesion." (PMID 32457603, 2020). "In cervical cancer, ITGA5 influences tumor cell responses to CXCL12 by regulating CXCR4 expression, thereby promoting cell migration and invasion." (PMID 40517358, 2025). "A genetic analysis of cervical cancer tumor tissue was conducted to assess the expression of STAT3, Snail, PD‐1, HPV16, HPV18, FOXP3, EXPORTIN 5 (XPO5), CXCR4, CXCL12, and CD8." (PMID 41263059, 2025).
cervical carcinoma (continued). "A new cytokine (CXCL16) was investigated together with the chemokine receptor combination CXCL12/CXCR4 and CXCL16/CXCR6 in cervical intraepithelial neoplasia (CIN) and cervical cancer." (PMID 34833360, 2021). "In contrast to former studies, a more recent study shows that the chemokine CXCL12 and its receptor CXCR4 are constitutively overexpressed in human cancers, especially cervical cancer." (PMID 34833360, 2021). "A particular significance correlation was found between CXCL12 and FOXP3 in cervical neoplastic lesion, suggesting that high levels of CXCL12 leads to retention or accumulation of FOXP3+ T cells in progressing cervical cancer." (PMID 30227860, 2018). "In cervical cancer, these mediators remodel the tumor microenvironment (TME) by orchestrating angiogenesis, epithelial-mesenchymal transition (EMT), and metastatic dissemination, where CXCR7 has demonstrated prognostic significance through CXCL12-mediated migration regulation." (PMID 40517358, 2025). "In addition, the suppression of CXCR7 can inhibit the progression of cervical cancer cells induced by CXCL12, but CXCR4 is not involved in these processes." (PMID 35264069, 2022).
lupus (27 papers, 2012 to 2026). "A previous study found that NZB/W mice susceptible to lupus had elevated CXCL12 levels in the kidneys, contributing to lupus nephritis." (PMID 39070795, 2024). "Increased CXCL12 levels in lupus-prone mice have been associated with improved SLE symptoms when treated with specific peptides, suggesting its role in the disease’s pathogenesis." (PMID 39070795, 2024). "Among these factors, CXCL12 has been associated directly with lupus disease activity both in active lupus nephritis patients and in several lupus mouse models." (PMID 29463843, 2018). "The results underline the importance of the CXCL12/CXCR4 axis in lupus pathophysiology." (PMID 34744730, 2021). "In this lupus mouse model, abnormally sensitive PerB1a lymphocytes to CXCL12 and IL-10 contribute to the development of autoimmunity." (PMID 39070795, 2024). "For example, secretion levels of CCL2, CCL3, CCL4, CCL5, CCL19, CXCL10, and CXCL12 are increased in the kidney of lupus-prone mice and SLE patients during the development of nephritis." (PMID 37567910, 2023). "Another study revealed increased migration of basophils in patients with systemic lupus erythematosus toward CXCL12 compared to those from healthy controls." (PMID 36618424, 2022). "Dysregulation of CXCL12/SDF-1-CXCR4/CD184 signaling is associated with inflammatory diseases and notably with systemic lupus erythematosus." (PMID 34744730, 2021). "In this report, we examined the in vivo effect of LIT-927 in diseased MRL/lpr lupus-prone mice and found that the CXCL12 neutraligand LIT-927 significantly reduces peripheral hypercellularity that characterizes this mouse model." (PMID 34744730, 2021). "This is the first study describing a neutraligand of the CXCL12 chemokine able to diminish inflammatory responses in lupus." (PMID 34744730, 2021). "In the (NZBxNZW)F1 lupus mouse model, CXCL12 is produced in situ in the inflamed glomeruli, podocytes and to a lesser extent, endothelial and mesangial cells produce large amounts of CXCL12." (PMID 34744730, 2021). "They indicate that neutralizing CXCL12 by the neutraligand LIT-927 can attenuate hyperactive lymphocytes in lupus." (PMID 34744730, 2021). "Among Chinese Han individuals, genetic variations of CXCL12-3′G801A are involved in the pathogenesis of systemic lupus erythematosus." (PMID 28589131, 2017). "The direct role of CXCL12/CXCR4 network to recruit immune cells in the lupus nephritic kidney is demonstrated in another study with administration of a CXCR4 antagonist in B6.SleYaa lupus-prone mice." (PMID 27403037, 2016). "Blocking the interaction of CXCL12/CXCR4 in lupus-prone mice reveals their contributions to both systemic autoimmune responses in secondary lymphoid organs and local renal inflammation." (PMID 27403037, 2016). "CXCL12 aberrantly mediated actin polymerization in the lupus mouse (red histogram) compared with the non-lupus control mouse (yellow histogram)." (PMID 25909640, 2015). "We found that the percentage of CXCL12-mediated actin polymerization every 15 seconds was significantly and aberrantly increased in lupus mice compared with the non-lupus control group (* P < 0.05)." (PMID 25909640, 2015). "In one representative experiment, the percentage of migrated CD45R/B220-FITC-positive B cells from a non-lupus control mouse was 9% in medium alone versus 48% in medium plus CXCL12." (PMID 25909640, 2015). "In addition, aberrant CXCR4 expression has been shown to correlate with autoimmunity in lupus and CXCL12/CXCR4 signaling regulates T cell migration to target organs in Sjögren’s syndrome." (PMID 35947323, 2022). "In mice, both PGD2 and CXCL12 have also been shown to be important in basophil trafficking to secondary lymphoid organs in a murine lupus model, while other studies showed CCL7-dependent migration to the draining lymph nodes in a context of pancreatic tumor or type 2 skin inflammation." (PMID 36618424, 2022).